IL10 (interleukin 10)
Diseases named in the same sentence as IL10 in open-access papers (continued):
Sharing a sentence is not in itself a finding about the gene and the disease.
Sepsis (continued). "IL-10 is pivotal in modulating immune responses, making it essential in the context of sepsis management." (PMID 39507174, 2024). "Recent studies from 2022 and 2023 have demonstrated the use of procalcitonin and IL-10 in early sepsis diagnosis and disease severity assessment in surgical patients." (PMID 39507174, 2024). "This review will focus on IL-6, IL-1β, TNF-α, and IL-10 due to their well understood pathology in sepsis to further explore the shared pathophysiology of sepsis across both humans and horses." (PMID 39273060, 2024). "Neutralizing IL-10 in animal models of sepsis increases inflammatory cytokine production and mortality, while administering recombinant IL-10 offers therapeutic benefits." (PMID 39507174, 2024). "In septic conditions, regulatory B (Breg) cells have an increasing circulation number and negatively regulate the innate immune responses mainly by secreting anti-inflammatory cytokines such as IL-10 and promote Treg cell reaction in sepsis." (PMID 39040114, 2024). "In HIV patients, elevated cytokine levels of interleukin (IL)-1, IL-6, IL-10, and tumor necrosis factor (TNF) are associated with the pathogenesis of sepsis in acute cases." (PMID 39676169, 2024). "Among these biomarkers, IL-10 exhibits the highest predictive capacity for the progression of infection to sepsis." (PMID 39212218, 2024). "Overall, our results identify α-GalCer-mediated induction of IL10 by iNKT and B cells as a promising option for controlling the pathogenesis of postoperative sepsis." (PMID 39355237, 2024). "On analyzing our cohort population, the importance of CRP, PCT, and IL-10 in diagnosing and managing sepsis is more evident." (PMID 39507174, 2024). "IL-10 is an anti-inflammatory cytokine that is needed to predict the worst outcomes of sepsis, such as multiple organ dysfunction syndrome (MODS) and immune system modulation." (PMID 39507174, 2024). "In bacterial infectious diseases, such as septicemia, the increase of serum concentration of IL-1, IL-6, IL-8, IL-10, and TNF-α is generally earlier than the clinical manifestation of the newborn." (PMID 38848433, 2024). "In this study, we discovered that IL-10 was the most effective predictor for progression from infection to sepsis and for assessing the prognosis of patients with infection." (PMID 39212218, 2024). "This understanding contributes to elevated blood IL-10 levels acting as a possible marker of sepsis-induced immunosuppression." (PMID 38255280, 2024). "The levels of IL-10 and IL-6 are elevated in sepsis, indicating a mixed hyperinflammatory and immunosuppressed status." (PMID 38696304, 2024). "Similar findings were observed in our study, indicating that patients with significantly elevated serum IL-6 and IL-10 concentrations at an early stage have the ability to predict progression to sepsis and ICU admissions." (PMID 39212218, 2024). "We found that the levels of IL-6, TNF-α, and IL-10 in the serum were upregulated in CLP-induced sepsis mice than those in sham group." (PMID 37776443, 2024). "Combining IL-10 with the NEWS score provides a reliable tool for predicting the progression from infection to sepsis at an early stage." (PMID 39212218, 2024). "Related to the aspect of immune cell exhaustion discussed earlier, another valuable marker of late sepsis that has been widely accepted is elevated levels of IL-10 in the serum." (PMID 38255280, 2024). "Curcumin was found to improve survival and regulate proinflammatory cytokines (TNF-α, IL-6 and IL-1β) and anti-inflammatory cytokines (IL-2 and IL-10) in mice with sepsis/ALI induced by CLP." (PMID 39051370, 2024). "IL-10 and NEWS had the strongest association with sepsis development, whereas IL-6 and CRP had the strongest association with ICU admission and in-hospital mortality." (PMID 39212218, 2024).
Sepsis (continued). "Interleukin-10 (IL-10) is an important anti-inflammatory cytokine in the pathophysiology of sepsis, which seeks to counteract the actions of pro-inflammatory mediators by reducing the synthesis and release of these mediators while antagonizing their effects." (PMID 38338117, 2024). "This study showed that CD86%, PLT, IL-10, and PCT were independent risk factors for sepsis in patients with infection, while HLA%, PLT, and respiratory rate were independent risk factors for death in patients with sepsis." (PMID 38603712, 2024). "CD39high plasmablasts, an expanded B cell subpopulation in CLP-induced sepsis, elevate extracellular adenosine, impair macrophages’ bactericidal activity, and enhance IL-10 production via the A2A adenosine receptor." (PMID 39040114, 2024). "Cmtm3 KO reduced the release of TNF-α, IL-1β, and IL-10 in the peripheral blood of CLP-induced sepsis mice, while TLR4 overexpression reversed this protective effect." (PMID 39455728, 2024). "We aimed to study the diagnostic significance of conventional (PCT and CRP) and new (IL-10) markers in accurately identifying sepsis and assessing its progression toward irreversible sepsis, shock, and multiorgan dysfunction." (PMID 39507174, 2024). "Serum IL-10 level in CLP-induced sepsis mice showed an increasing trend and reached a peak at 72 h (P = 0.002)." (PMID 37776443, 2024). "We also showed that irisin was negatively associated with most inflammatory biomarkers (CRP, procalcitonin, IL-6, IL-10) at sepsis onset, in accordance with in vitro studies." (PMID 38540711, 2024). "Sepsis is associated with high levels of inflammatory cytokines such as TNF-α, IL-1β, IL-6, and IL-10." (PMID 39597952, 2024). "Genetic variation factors affect the amount of IL-10 secreted by cells in the body, so as to further regulate sepsis." (PMID 38848433, 2024). "On the contrary, in the later stages of sepsis, excessive increase of M2-type macrophages will secrete more anti-inflammatory factors IL-10, transforming growth factor-β (TGF-β), etc., contributing to immune suppression in the host." (PMID 39624773, 2024). "Patients exhibiting low severity signs of infection but high IL-10 levels showed an elevated probability of developing sepsis." (PMID 39212218, 2024). "In sepsis, IL-10 plays a dual role: it reduces harmful inflammation but can also impair immune responses, contributing to poor outcomes." (PMID 39507174, 2024). "Decreased lymphocytes, decreased expression of monocyte HLA-DR, and overexpression of IL-10 are indicators of sepsis-induced immunosuppression." (PMID 38603712, 2024). "Not only does the patient’s IL-10 level correlate with his/her sepsis severity score, but it also has been reported to be a major risk factor for increased clinical severity." (PMID 38255280, 2024). "In sepsis patients, anti-inflammatory reactions are recognized with the pro-inflammatory response (The increase of IL-10 correlated with the rise of TNF-alpha, IL-6, and IL-8.)." (PMID 38375470, 2024). "Administration of anti-PD-L1 antibodies prevented sepsis-induced monocyte dysfunction and decreased TNF-α, IL-6, and IL-10 production at different stages of sepsis, implying an overall reduction in systemic inflammation." (PMID 37776443, 2024). "This contrast in findings between neonatal and adult horses highlights current gaps in understanding regarding the role of IL-10 in the pathology of endotoxemia and sepsis in horses." (PMID 39273060, 2024). "The biphasic temporal response of IL-10 in sepsis should also be considered for optimal timing of IL-10 therapy." (PMID 38504987, 2024). "The second related to diminished release of anti-inflammatory IL-10, which prevented immune suppression and bacterial dissemination in the late phase of sepsis." (PMID 38982113, 2024). "To provide evidence that IL10-mediated immune responses correlate with protection against sepsis pathogenesis in human, we performed GSEA on PBMCs of groups of sepsis survivors and non-survivors." (PMID 39355237, 2024).
Sepsis (continued). "The JAK/STAT pathway is a prominent signaling cascade activated by several critical cytokines implicated in sepsis, such as IFN-γ, IL-4, IL-6, IL-10, and IL-12." (PMID 39062636, 2024). "Despite typically producing low cytokine amount, neutrophils in sepsis are notable for increased interleukin (IL)-10 production." (PMID 38474403, 2024). "Clinical sepsis related immunoparalysis is known to present with an anti-inflammatory innate immune phenotype that is hallmarked by increases in IL-10 concentrations." (PMID 39075164, 2024). "The significance of the observed increase in IL-10 secretion from Foxp3+ CD8+ T cells during sepsis is based on studies showing that IL-10 can be both beneficial and detrimental to survival during sepsis." (PMID 38633258, 2024). "A recent study demonstrated that IL10+ macrophages expanded during LPS-induced sepsis promote homeostasis and survival." (PMID 39355237, 2024). "Our results showed that the anti-PD-L1 antibody markedly decreased the level of serum inflammatory cytokines interleukin (IL)-6, tumor necrosis factor (TNF)-α, and IL-10 in sepsis mice at 24 h, 48 h, and 72 h, respectively (P < 0.05)." (PMID 37776443, 2024). "Overall, the complexities of translating IL-10 modulation into effective sepsis treatments warrant further mechanistic characterization." (PMID 38504987, 2024). "In this two-sample MR study leveraging GWAS summary data of European populations, we found evidence supporting causal effects of genetically predicted circulating IL-10, MCP-1 and MIP1B levels on sepsis risk and related outcomes." (PMID 38504987, 2024). "In sepsis, high levels of IL-10 are critical for controlling inflammatory responses that can cause tissue damage." (PMID 39527629, 2024). "Currently, a variety of biomarkers are employed to aid in the clinical diagnosis of sepsis, including C-reactive protein, P-selection, vascular cell adhesion molecule-1, programmed death-1, interleukin 6, interleukin 10, etc.." (PMID 38255822, 2024). "For cytokine profiles, the levels of both proinflammatory (such as IL-6, GM-CSF, and CXCL10) and anti-inflammatory (such as IL-1ra, IL-10, and PD-L1) cytokines were increased in bacteremia and sepsis patients compared to HCs." (PMID 38707899, 2024). "Together, these findings highlight a significant role of an IL-10/DEL-1 axis in preventing sepsis-induced neutropenia and promoting survival from sepsis in neonates." (PMID 38263289, 2024). "Diminished production of IL-10 has been correlated with the severity and mortality rates in patients with sepsis." (PMID 38504987, 2024). "It has been found that an inflammatory response that is too low in the expression of anti-inflammatory cytokines has a significant impact on the onset of sepsis; therefore, IL-10 can regulate the occurrence, development and prognosis of sepsis." (PMID 38848433, 2024). "Five of the eleven biomarkers (IL-6, TNF-α, IL-8, IL-10, and sST-2) were significantly higher in patients with GN sepsis or NEC than those with NS, CS, and GP sepsis (p < 0.05)." (PMID 38312920, 2024). "Similar to other studies, the elevated levels of IL-10 during the course of the study indicate its involvement in the sepsis response." (PMID 39507174, 2024). "Upregulating IL-10 production was reported to ameliorate bacterial outer membrane vesicle-induced sepsis in mice 48, thus raising the possibility that the increased IL-10 contributed to BPE-mediated anti-inflammation effects in this study." (PMID 38164360, 2024). "IL-6 and IL-10, which have better predictive ability for sepsis among all immune response biomarkers, as well as CRP, PCT and clinical scores were selected for further analysis of their relationship with secondary endpoints." (PMID 39212218, 2024). "In human patients with sepsis, an IL-10 blockade has been shown to decrease survival and increase neutrophil activation." (PMID 39273060, 2024).
Sepsis (continued). "A comprehensive analysis was conducted to investigate the impact of senescence-related genes on sepsis, and 8 hub genes (IGFBP7, GMFG, IL10, IL18, ETS2, HGF, CD55, MMP9) associated with senescence were identified." (PMID 38259686, 2023). "The inflammatory markers IL-6, IL-10, and TNF-α are all strongly linked to the onset of sepsis, and as one of the most important inflammatory cytokines, TNF-α stimulates the production of IL-6 in endothelial cells." (PMID 36644442, 2023). "In patients with sepsis, the percentage of IL-10-producing Bregs decreased significantly compared to healthy controls, and this decrease was more pronounced in nonsurvivors than in survivors." (PMID 37128298, 2023). "Two studies reported outcomes of IL-10 in the detection of sepsis, the pooled sensitivity was 0.89 (95% CI: 0.79, 0.95; I2 = 65.3%, p = 0.090) and the pooled specificity was 0.83 (95% CI: 0.75, 0.89; I2 = 0%, p = 0.523), respectively." (PMID 38027268, 2023). "MSCs can secrete interleukin-10 (IL-10), and in a study using a sepsis model in mice, MSCs displayed the ability to bolster IL-10 production." (PMID 38002286, 2023). "Patients with sepsis had increased serum levels of IL-6, IL-10, IFN-γ, and neutrophil HSP90α expression compared to controls but repressed monocyte HSP90α." (PMID 36615909, 2023). "IL-10 serum levels have been correlated with the severity and the clinical outcome in sepsis, septic shock and CAP and with a fulminant course of S. pneumoniae infection in a murine model of P-CAP." (PMID 38143267, 2023). "These macrophages are responsible for reducing cytokine levels, including IFNγ, TNF, IL-6, and IL-10, in patients with sepsis." (PMID 38193079, 2023). "IL-8 and IL-10 concentrations were highest in the sepsis-induced MODS group at all moments, from T0 to T2." (PMID 37441100, 2023). "In sepsis, simultaneously elevated levels of pro-inflammatory cytokines and interleukin (IL)-10 indicate immune response dysregulation, increasing the mortality of the host." (PMID 37626822, 2023). "Serum levels of IL-1β and IL-6 also significantly decreased with the use of curcumin in the treatment of sepsis, while IL-10 showed increased plasma levels." (PMID 36756300, 2023). "ELISA-based detection of the levels of TNF-α, IL-6, and IL-10 in the peripheral blood of mice 24 h after CLP induction revealed that cytokine content in the peripheral blood increased during the development of sepsis." (PMID 37434129, 2023). "Compared to immunized, isotype control antibody-treated mice, immunized mice depleted of IL-10 during lethal sepsis challenge had significantly higher mortality (P = 0.002), and similar mortality levels to nonimmunized control mice." (PMID 37681975, 2023). "Correlation analysis between IL10 and immune cells in the sepsis group identified a strong positive correlation between IL10 and macrophages, providing a theoretical basis for the therapeutic effect of IL10‐modified engineered macrophages on sepsis." (PMID 37060578, 2023). "Our research showed that plasma IL-10 levels were significantly increased in all patients with sepsis, especially in the septic shock and 28-day mortality groups." (PMID 36721090, 2023). "For example, high levels of IL-10 have been shown to be a useful predictor of severity in septic shock and death and have been correlated with poor prognosis of sepsis in adults." (PMID 38287976, 2023). "Compared to healthy subjects, LPS induced MCP-1 in PBMCs of patients with sepsis at 48 h (p < 0.001) but repressed IL-10 at 24 (p = 0.001) and 48 h (p < 0.001)." (PMID 36615909, 2023). "Remarkably, B-1a cells have reduced excessive inflammation during sepsis by producing large amounts of IL-10 and granulocyte-macrophage colony-stimulating factor in a mouse model of sepsis." (PMID 37128298, 2023).
Sepsis (continued). "As mesenchymal stem cell (MSC) secretome is known to have immunomodulatory effects, we aim to assess the role of MSC secretome in the inflammatory mediators (NF-κB p65 and p50, TNF-α, IL-10) and the survival rate of a rat model of sepsis." (PMID 37626822, 2023). "The plasma concentration of IL‐10 increased to peak levels by 8 h of sepsis (0.5 ± 0.6 to 4.1 ± 2.1 ng mL−1) and remained elevated at 24 h in vehicle‐treated sheep (3.1 ± 1.7 ng mL−1) and was not affected by RAT and IVT." (PMID 37548350, 2023). "IL-10, in particular, can inhibit phagocytosis and represents a biomarker of the immunosuppressive phase of sepsis." (PMID 37762478, 2023). "IL-10 promotes sepsis-induced immunosuppression and supports S100A9 protein translocation to the nucleus in mouse MDSCs during late sepsis." (PMID 39665047, 2023). "For example, transcutaneous auricular VNS can significantly inhibit the production of proinflammatory cytokines (e.g., TNF-α and IL-1β) and increase the production of anti-inflammatory cytokines (e.g., IL-4 and interleukin 10 (IL-10)) in sepsis patients." (PMID 37767094, 2023). "Studies have demonstrated that IL-10 secreted by macrophages, particularly immune cells, is a critical factor in the battle against sepsis." (PMID 37561521, 2023). "In animal models of severe sepsis, elevated levels of IL-10 expression are crucial for limiting tissue damage and improving host survival." (PMID 37237294, 2023). "We found that IL-10-secreting B cells are present in patients with sepsis-induced ARDS and had a higher percentage than other PBMC cells (including DCs, monocytes, and CD4+/CD8+ T cells)." (PMID 37443161, 2023). "IL-10 is also released into the circulation during human sepsis and controls the production of TNF, IL-1, and IL-8 in vitro." (PMID 37004108, 2023). "Another possibility of the mechanism was that NRBCs seem to have a regulatory function via the induction of IL-10 production by monocytes to suppress a vigorous innate immune reaction, as IL-10 plays a detrimental role in sepsis." (PMID 38029254, 2023). "The detection performance of IL-27, IL-8, and IL-10 in late-onset sepsis ranked from superior to inferior based on the superiority index." (PMID 38027268, 2023). "In this study, we identified 8 senescence-related genes (IGFBP7, GMFG, IL10, IL18, ETS2, HGF, CD55, and MMP9) and developed a diagnostic model for the prediction of sepsis occurrence." (PMID 38259686, 2023). "These cells coordinately mediate immunosuppression by releasing anti-inflammatory cytokines such as interleukin 10 in patients with sepsis." (PMID 37853324, 2023). "Overproduction of IL-10 can lead to a compensatory anti-inflammatory response and inhibit the inflammatory defense system in patients with sepsis." (PMID 37753078, 2023). "Comparisons involving the therapeutic effect of wild-type ASCs and ASCs transiently expressing CXCR4 and IL-10 were carried out with the aim of generating an improved anti-inflammatory response for sepsis in addition to standard antibiotic treatment." (PMID 38203690, 2023). "In conclusion, the present study identified core immune‐related DEGs between severe burns and sepsis, including IL10, RETN, THBS1, FGF13, LCN2 and MMP9." (PMID 37060578, 2023). "IL-8 showed the most optimal properties in the diagnosis of early-onset sepsis in neonates as compared to IL-6, IL-8, IL-10." (PMID 38027268, 2023). "Based on the median expression levels of IL10, the IE (GSE29161) and sepsis datasets (GSE57065) were divided into high IL10 expression and low IL10 expression groups." (PMID 38332910, 2023). "We also focused on IL-10 as a potential therapeutic target, providing scientific rationale for the potential application of small molecule drugs in treating IE and Sepsis." (PMID 38332910, 2023).